IL1B (interleukin 1 beta)
Diseases named in the same sentence as IL1B in open-access papers (continued):
Sharing a sentence is not in itself a finding about the gene and the disease.
hyperlipidemia (72 papers, 2010 to 2026). "Elevation of IL-1β levels leads to chronic low-grade inflammation, cytokine profile changes and activation of innate immunity, and the increased expression of IL-1β in plasma/serum can alter lipid metabolism, causing hyperlipidemia." (PMID 34867336, 2021). "Given the background of the ApoE-deficient mouse model of hyperlipidemia, Rac2 deletion resulted in elevated circulating IL-1β in blood plasma from mice on a cholesterol-supplemented high-fat diet." (PMID 34831028, 2021). "A prominent feature of HFD-triggered hyperlipidemia is the accumulation of lipid, as well as promoting low-grade chronic inflammation associated with increased levels of mediators such as IL-1β, IL-6, and TNF-α." (PMID 32089647, 2020). "Research has revealed that hyperlipidemia level is highly connected with m6A-SNPs and FTO-associated inflammatory factor IL-1β, IL-6, and LPS which induce hyperlipidemia may be the factors in the development of chronic heart disease." (PMID 36157445, 2022). "Chronic exposure to proinflammatory cytokines, such as TNF-α and IL-1β, may alter lipid metabolism, causing hyperlipidemia." (PMID 34203460, 2021). "Hyperlipidemia causes adipocyte hypertrophy and fat accumulation in extra-adipose tissues such as liver and muscle tissues, leading to increased oxidative stress and release of cytokines, such as TNFα, interleukin (IL)-6, and IL-1β." (PMID 33922045, 2021). "Experimental studies indicate that asprosin can trigger proinflammatory responses in THP-1 macrophages, increasing secretion of TNF-α, IL-1β, IL-6, IL-8, and IL-12, and promotes hyperlipidemia-induced endothelial inflammation via NF-κB signaling." (PMID 41286678, 2025). "In hyperlipidemia, IL‐1β, IL‐6, IL‐8, and IL‐10 still had significant differences between the SAP group and non‐SAP group (p < .05), while IL‐5, IL‐17, TNF‐α had no statistical differences between the two groups." (PMID 38411379, 2024). "The expressions of NLRP3 and IL-1β were significantly increased in obese models with hyperlipidemia compared to those with normal lipids." (PMID 36557935, 2022). "With the condition of IR, hyperlipidemia increased the IL-1β and TNF-α levels further, and they were reduced by pre-treatment with TIIA." (PMID 36279396, 2022). "PBMC from patients with hyperlipidemia, when treated in vitro with recombinant IL‐38, reduced gene expression and protein secretion of IL‐6, IL‐1β, and CRP." (PMID 33125159, 2021). "SNPs associated with IL1F10 are associated with serum C‐reactive protein (CRP) concentrations in a genome‐wide association study, and recombinant IL‐38 inhibits CRP and IL‐1β production by PBMC from patients with hyperlipidemia." (PMID 33125159, 2021). "With hyperlipidemia, fatty acids and cholesterol crystals increase, possibly activating the Nalp3-inflammasome and leading to increased release of IL-1β, one of the critical pro-inflammatory cytokines involved in the development and progression of KOA28–30." (PMID 28852192, 2017). "All HSYA groups ameliorated the excessive production of TNF-α and IL-1β in rat hearts induced by MI/R superimposed on hyperlipidemia injury." (PMID 27731393, 2016). "All HSYA groups ameliorated the excessive production of TNF-α and IL-1β in serum induced by MI/R+hyperlipidemia injury." (PMID 27731393, 2016). "The hyperglycemic state and hyperlipidemia in turn activate glycation end products (AGEs), whose receptors are on monocytes, endothelial cells and macrophages, which secrete interleukin 1β (IL-1β), interleukin 6 (IL-6), Prostaglandin E2 (PGE2) and tumor necrosis factor alpha (TNF-α)." (PMID 40141192, 2025). "On the other hand, hyperlipidemia also increases the amount of IL-1β and TNF-α." (PMID 40141192, 2025). "The CANTOS trial demonstrated that specifically targeting IL-1β with the monoclonal antibody canakinumab reduced chronic low-grade inflammation and the incidence of cardiovascular events, independently of other factors such as hyperlipidemia." (PMID 38225643, 2024).
hyperlipidemia (continued). "In addition, exercise reduced the hyperlipidemia-induced increase in the expression of inflammatory signals, including IL-1β, IL-6, and IL-18, in kidney tissue." (PMID 37277452, 2023). "MG induced Nrf2/HO-1 signaling, diminished Tylo-induced hyperlipidemia, oxidative stress, IL-1β as well as TNF-α and IL-6 that might arise from the suppression of NLRP3 inflammasome." (PMID 32992548, 2020). "It was hypothesized that proinflammatory cytokines from GCF or systemic circulation, such as TNF-α, IL-1β, and IL-6, induce hyperlipidemia due to enhanced hepatic lipogenesis, increased synthesis of triglycerides, and reduced clearance of both triglycerides and LDL." (PMID 36983201, 2023). "Moreover, hyperlipidemia–induced dysbiosis can lead to disorder of the local immune system, accompanied by production of inflammatory cytokines such as IL–1β, IL–6, and tumor necrosis factor (TNF)–α, and adipokines such as leptin in addition to increasing the intestinal permeability." (PMID 36364184, 2022). "Pro-inflammatory cytokines such as IL-1β, TNF-α, and IL-17 disrupt systemic lipid homeostasis by suppressing lipoprotein lipase and promoting hepatic lipogenesis, leading to hyperlipidemia." (PMID 41508030, 2026). "In fact, TNF-α amniotic acid together with increased IL-1β results in increased protein kinase C (PKC), the destruction of pancreatic β-cells and a synergistic increase in hyperlipidemia through lipid clearance, increased lipogenesis and decreased lipolysis." (PMID 40141192, 2025). "Inhibited fat accumulation and body weight, hyperlipidemia; reduced LPS level; decreased levels of TNF-α and IL-1β; increased acetate and butyrate production; inhibited LPS/TLR4/NF-κB signaling pathway." (PMID 36671814, 2023). "Our data confirmed that increased hyperlipidemia-mediated inflammation activated HMGB1-TLR4 signaling, NLRP3 inflammasome formation, and upregulation of pyroptosis markers caspase-1, IL-1β, IL-18, and the pyroptosis executor GSDMD." (PMID 36829889, 2023). "Hyperlipidemia results in the upregulation of NLRP3, caspase-1, and IL-1β, and leads to pyroptosis in ECs." (PMID 33339328, 2020). "Treatment with SREBP decoy ODN remarkably decreased the expression of TNF-α, IL-1β, and IL-8, more than the Scr decoy ODN did in HFD-induced hyperlipidemia mice." (PMID 31952262, 2020). "Hyperlipidemia can induce systemic inflammation and increase the NF-κB signaling and TNF-α and IL-1β expression in animals." (PMID 30050930, 2018). "Meanwhile, MI/R+hyperlipidemia group demonstrated significantly higher levels of TNF-α and IL-1β in rat hearts than I/R group (P < 0.01)." (PMID 27731393, 2016). "The results showed that hyperlipidemia stimulated the excessive expression of TNF-α and IL-1β in serum of myocardial I/R group." (PMID 27731393, 2016). "Meanwhile, MI/R+hyperlipidemia group had significantly higher levels of TNF-α and IL-1β in serum than I/R group (P < 0.01)." (PMID 27731393, 2016). "Therefore, investigating the relationship between inflammation and hyperlipidemia using other inflammatory markers, including high-sensitivity CRP, TNF-α, and IL-1β, is necessary." (PMID 40552326, 2025). "In case of liver inflammation related genes (IL-1β, TNF-α, IL-6, IL-18, CCL20, and NF-κB) their expression levels were significantly (P < 0.05) upregulated and IL-1RN was significantly (P < 0.05) downregulated in the liver of hyperlipidemia group." (PMID 41144456, 2025). "HFD induces hyperlipidemia proven by increased plasma concentration of CT, LDL-C, and TG, which initiates an inflammatory response, supported through increased inflammatory biomarkers (hs-PCR, TNF-α, IL-1β, IL-6) compared to the BD group." (PMID 35204113, 2022). "In addition, HFD-induced hyperlipidemia mice liver tissues showed an increased mRNA level expression of TNF-α, IL-1β, and IL-8." (PMID 31952262, 2020).
hyperlipidemia (continued). "Our single cell RNA-Seq data analysis results showed that CD95, TNF-α and IL-1β are co-expressed in CD95+ monocytes and macrophages in aortas and peripheral blood, and CD95 expressions are increased in MHO aortas in hyperlipidemia conditions." (PMID 33488632, 2020). "High-fat diet induced hyperlipidemia worsened MI/R mediated heart injury (elevation of infarct size, CK-MB and LDH activity), activated TLR4 over-expression in hearts, released inflammatory cytokines (LPS, TNF-α and IL-1β) excessively." (PMID 27731393, 2016). "Meanwhile, hyperlipidemia up-regulated the expression level of cardiac TNF-α and IL-1β." (PMID 27731393, 2016). "In our study, the HLD induced hyperlipidemia, which is highlighted by higher serum levels of TC, LDL-C, and initiated an inflammatory process shown by higher serum levels of inflammation markers (hs-PCR, TNF-α, IL-1β, IL-6) in the HLD group compared to the group fed with SD." (PMID 34300308, 2021). "In addition, SREBP decoy ODN decreased AST, ALT, total cholesterol, and triglyceride levels in the serum of hyperlipidemic mice fed with HFD, and furthermore, significantly inhibited the pro-inflammatory cytokine expressions of IL-6, TNF-α, IL-1β, and IL-8 in HFD-induced hyperlipidemia mouse models." (PMID 31952262, 2020). "To test whether hyperlipidemia sharpened the inflammatory response induced by myocardial I/R through the up-regulation of the secretion of pro-inflammatory cytokines, we analyzed the expression of pro-inflammatory cytokines TNF-α and IL-1β in serum." (PMID 27731393, 2016). "Furthermore, hyperlipidemia may induce NLRP3 inflammasome activation in immune cells and produce large amounts of IL-1β, leading to phenotype transformation of VSMCs and synthesis and secretion of MMPs stimulated by IL-1β produced after immune cell infiltration." (PMID 38992615, 2024). "Taken together, our results provide insights into the roles of gram-negative bacteria in gut-generated LPS and intracellular gram-negative bacterial infections in CKD and hyperlipidemia pathologies activating CASP4/11-GSDMD and IL1B pathways." (PMID 39024553, 2024). "Moreover, HLF could significantly reduce the levels of NLRP3, caspase-1, IL-1β, IL-6, IL-18, and TNF-α and increase the activities of plasma SOD, CAT, and GSH-PX, which suggested that HLF could effectively relieve the inflammatory response and oxidative stress induced by hyperlipidemia." (PMID 36425260, 2022). "Moreover, orally active trans-PAO did not reduce or induce hyperlipidemia-induced IL-1β levels in the plaques or in the serum of Apoe−/− mice, which was consistent with our observations on trans-PAO's impact on IL-1β secretion in macrophages." (PMID 31422082, 2019). "Interestingly, TNFα and IL-1β have also been shown to induce VCAM-1 expression by this pathway and may account in the absence of hyperlipidemia but under hyperglycemic conditions (such as in the diabetic wt mice in this study), for the observed up-regulation of VCAM-1 in retinal vessels." (PMID 20856927, 2010).
ulcer (72 papers, 2007 to 2025). "H. pylori associated ulcer patients have significantly lower level of IL1B than infected asymptomatic individuals." (PMID 21445336, 2011). "As both the production of cytokines at the lesion site and the size of the ulcers were quite variable, to better evaluate the association between IL-1β, IL-17, and GzmB with lesion size, we compared these cytokine levels in the supernatants of skin biopsies with the size of the ulcers." (PMID 38535542, 2024). "Moreover, the production of several cytokines, including IL-1β, in gastric mucosa is increased in subjects infected with H. pylori, and this infection has been associated with ulcer recurrence." (PMID 35463093, 2022). "Besides ulcer prevention, L. squarrosulus mycelia extract was also able to heal ulcer and this was associated with the attenuation of proinflammatory cytokines IL-1β and the inhibition of NF-κB in ulcerated rats." (PMID 21423634, 2011). "Adjusting for age, place of origin, schooling, smoking habits, family history of gastritis or gastric ulcer, and H. pylori infection, TC/CC of IL-1B -511 T>C SNP was significantly associated with ulcer and chronic gastritis together, as compared to controls (OR = 2.9, 95% CI = 1.4-5.8, p = 0.004)." (PMID 20979650, 2010). "Immunohistochemical analysis and in situ hybridization with interleukin-1β (IL-1β) showed a high expression of IL-1β only in injured areas, suggesting that IL-1β may be involved in the formation of ulcers in patients with intestinal BD carrying MEFV gene mutations." (PMID 37176572, 2023). "In H. pylori-infected ulcer patients, upregulation of active IL-1β and downregulation of pro-IL-1β were seen in 45.5% of the population, compared with 26.7% of infected gastritis patients." (PMID 40563885, 2025). "Pro-IL-1β levels increased with infection in gastritis cases but declined in ulcer patients, whereas mature IL-1β was elevated across both infected groups." (PMID 40563885, 2025). "Compared to the ulcer group, the Cls and Omp groups had significant reductions in IL-1β, IL-6, and TNF-α contents." (PMID 38884677, 2024). "This study emphasizes the ability of PRF-EMFs to modulate the TGFβ, COX2, IL6, IL1β, and TNFα gene expression in exposed ulcers." (PMID 38671778, 2024). "Patients presenting an ulcer size larger than 206 mm2 displayed significantly higher levels of IL-1β, IL-17, and GzmB in lesion cultures compared to patients whose ulcers were smaller than 206 mm2." (PMID 38535542, 2024). "As a result, suppressing the expression of pro-inflammatory cytokines such as TNF-α, IL-1β, and IL-6 effectively treats ulcer damage in the colon." (PMID 38791116, 2024). "Gastric TNF-α level was further reduced by NS-398 as compared to NPW-treated ulcer group (p < 0.05), while gastric IL-1β levels were depressed more with both of the specific COX-inhibitors (p < 0.05–0.01)." (PMID 38227096, 2024). "The levels of production of PGE2 and IL1β were evaluated in scratched normal-HDF, ulcer-HDF, and exposed ulcer-HDF supernatants to underline the differences between the cell lines." (PMID 38671778, 2024). "This faster healing on the tongue was further supported by significantly lower expression levels of TNF-α and IL-1β and a reduction in ulcer size, particularly on the tongue compared to the palate." (PMID 39739075, 2024). "The levels of IL1β show the same trend, with a slight increase in ulcer-HDFs and a more significant increase in exposed ulcer-HDFs with respect to normal-HDFs, in accordance with the increased cell proliferation and early scratch healing progression." (PMID 38671778, 2024). "Following ulcer induction, the gastric levels of IL-1β in the INDO group (2.439 ± 46.66 pg/mL) were found to be higher than the control group (1.780 ± 176.2 pg/mL); p < 0.001)." (PMID 36836745, 2023).
ulcer (continued). "Mucosal administration of HC peptides resulted in decreased gastric inflammation and reduced circulating amounts of the pro-inflammatory cytokine IL-1β in rats with stress-induced ulcers and acetic acid-induced ulcers." (PMID 37174535, 2023). "HMGB1 and Nuclear factor kappa (NF-B) expression, IL-1β and Nrf2 contents showed an increase along with ulcer development, concurrent with an increase in immunohistochemical TLR-4 level." (PMID 37371993, 2023). "Then, ulcer recurrence in these animals was induced by IL-1β at five days after the treatment period." (PMID 35463093, 2022). "EGb 761 treatment after ulcer development resulted in a substantial reduction in IL-1β expression when compared to the indomethacin group and EGb 761 pre-treated mice." (PMID 36080365, 2022). "To evaluate the anti-inflammation of the AAEs in ulcers, we detected the levels of proinflammatory and anti-inflammatory cytokines, including IL-1β, IL-6, and IL-10 in the serum." (PMID 34580595, 2021). "During oral ulceration, higher levels of IL-8 and IL-1β reflect mucosal damage and recruitment of inflammatory cells into the wound." (PMID 35003055, 2021). "TNF-α stimulates neutrophil infiltration, promotes IL-1β production and epithelial cell apoptosis, inhibits the recovery of microcirculation around ulcer, and delays ulcer healing." (PMID 34159200, 2021). "The exacerbated expression of IL-1β contributes to the formation of ulcers and stimulates the production of more TNF-α." (PMID 34497525, 2021). "F-AOH effectively reduced the ulcer index (from 23.4 ± 4.28 to 8.32 ± 1.5) and reduced release of inflammatory mediators (IL-1β, IL-6, TNF-α and PGE2), increased the content of nitric oxide and improved GAS and MTL secretion." (PMID 32871094, 2020). "Results of IL-1β and TNFα cytokines analysis showed that administration of both doses of Hypericum perforatum decreased the level of IL-1β and increased the level of TNFα cytokines in comparison to the ulcer control group (10% Tween 20)." (PMID 33102861, 2020). "Further, IL-1β markedly increases infiltration of leucocytes in the superficial portion of scarred mucosa prior to ulcer recurrence, while enhancing ICAM-1 expression." (PMID 26465592, 2015). "In addition, sodium butyrate significantly inhibited the mRNA levels of inflammatory factors such as tumor necrosis factor-α (TNF-α), interleukin-1β (IL-1β), interleukin-6 (IL-6), and interleukin-18 (IL-18) in the ulcer tissue." (PMID 40818135, 2025). "Our findings corroborate earlier research indicating that OMP, used as a reference drug, significantly diminished the levels of HMGB1, NF-κB p65, and NLRP3 in comparison to the ulcer group and substantially reduced the levels of IL-1β, IL-6, and TNF-α in gastric mucosa." (PMID 40563542, 2025). "Mature IL-1β was upregulated in the presence of ulcers in both control and infected patients." (PMID 40563885, 2025). "Thus, in this study, we evaluated the effect of the exposure to a PRF-EMF on ulcer-HDFs, observing a significant increase in the expression levels of IL1β, IL6, COX2, and TGFβ with respect to unexposed normal-HDFs and ulcer-HDFs." (PMID 38671778, 2024). "Notably, the strongest correlation between ulcer size and in situ cytokine production was detected with IL-1β (r = 0.86, p < 0.0001), followed by GzmB (r = 0.79, p < 0.0001) and IL-17 (r = 0.79, p < 0.0001)." (PMID 38535542, 2024). "Furthermore, Pioglitazone demonstrated a gastroprotective effect against ethanol induced ulcer via inhibition of nitric oxide synthase activity and decreasing the level of IL-1β and TNF-α." (PMID 38441571, 2024). "ELISA: IL-1β level in ulcers of MSC-CM or MSCs group was lower than that of DM-C group (p < 0.05)." (PMID 36948071, 2023). "They discovered that inhibiting gastric acid sufficiently with omeprazole prevented both ulcer recurrence and responses, indicating that acid may enhance gastric mucosal inflammation in response to IL-1β stimulation, resulting in gastric ulcers." (PMID 36712695, 2022).